EZH2 (enhancer of zeste 2 polycomb repressive complex 2 subunit)
Diseases named in the same sentence as EZH2 in open-access papers (continued):
Sharing a sentence is not in itself a finding about the gene and the disease.
Stroke (2 papers, 2013 to 2025). Sudden impairment of blood flow to a part of the brain due to occlusion or rupture of an artery to the brain. "This makes EZH2 a fascinating epigenetic link between neuroimmune therapies and peripheral immune responses post-stroke." (PMID 40723311, 2025). "Therefore during spinal cord injury or stroke, EZH2-induced overactivation of astrocytes will initially protect but subsequently, it will hinder axonal regrowth, and delay functional recovery." (PMID 40723311, 2025). "In animal model, rats implanted with intracerebral EZH2-knocked-down hMSCs or hMSCs plus treatment with PPARγ agonist (rosiglitazone) showed better improvement than those without EZH2 knockdown or rosiglitazone treatment after a stroke." (PMID 23526793, 2013). "In addition, our behavioural measurements of neurological deficit after stroke in a rat model showed better improvement after intracerebral implantation of hMSC with EZH2 knockdown than after implantation of hMSCs without EZH2 knockdown." (PMID 23526793, 2013).
subarachnoid hemorrhage (2 papers, 2021 to 2023). A serious neurological disorder characterized by intracranial hemorrhage into the subarachnoid space. "Deficient EZH2 activity has been implicated in the pathological processes of neurodegenerative diseases, while enhanced EZH2 activity contributes critically to neuroinflammation induced by subarachnoid hemorrhage and neuropathic pain." (PMID 37048131, 2023). "Furthermore, EZH2 inhibition can further ameliorate neuroinflammation following subarachnoid hemorrhage in rats, which underscores the neuroprotective function of EZH2 inhibition." (PMID 34422795, 2021).
testicular germ cell tumor (2 papers, 2022 to 2023). A germ cell tumor arising from the testis. "However, in testicular germ cell tumors, such a combination would not be recommended because cisplatin resistance seems to be associated with decreased expression of EZH2 in this tumor type." (PMID 36230683, 2022).
thymic carcinoma (2 papers, 2023 to 2025). Thymic carcinoma (TC) is a type of thymic epithelial neoplasm characterized by a high malignant potential. "We provide the first report of ≥80% EZH2 staining in thymic lymphoepithelial, sarcomatoid, undifferentiated, and adenosquamous thymic carcinomas." (PMID 37190202, 2023). "Independent validation on larger sample sizes, rare thymic carcinoma subtypes, and whole tissue sections remains to be performed for both EZH2 and POU2F3 in TETs." (PMID 37190202, 2023). "The addition of EZH2 increased the overall sensitivity for thymic carcinoma to 92% when used in combination with CD117." (PMID 37190202, 2023). "All thymic carcinomas had EZH2 staining in >10% of tumor cells, such that EZH2 staining in ≤10% of tumor cells could help exclude carcinoma." (PMID 37190202, 2023). "As all thymic carcinomas showed EZH2 staining in >10% of tumor cells, staining in ≤10% of tumor cells may provide evidence against the possibility of thymic carcinoma." (PMID 37190202, 2023). "Recurrent mutations in chromatin remodeling genes in thymic carcinoma implicate epigenetic dysregulation in the pathogenesis of thymic carcinoma, but the precise mechanism through which aberrant EZH2 expression may contribute to the development of TETs remains to be investigated." (PMID 37190202, 2023). "EZH2 staining in ≤10% of tumor cells may help to exclude the possibility of thymic carcinoma." (PMID 37190202, 2023). "CD5, CD117, EZH2, POU2F3, MTAP, and BAP1 have been proposed as useful markers for the distinction of thymic carcinoma from thymoma." (PMID 40242668, 2025). "We explored the relationship between CD5, CD117, EZH2, POU2F3, MTAP, and BAP1 immunoreactivity and the overall survival (OS) and progression-free survival (PFS) of patients with thymic carcinoma, using a cohort with diverse histologic subtypes." (PMID 40242668, 2025). "We aimed to determine the prognostic significance of CD5, CD117, EZH2, POU2F3, BAP1, and MTAP immunohistochemical staining in thymic carcinomas." (PMID 40242668, 2025). "We also caution that EZH2 and POU2F3 are detectable in non-thymic carcinomas, and immunoreactivity for these markers does not imply thymic origin." (PMID 37190202, 2023).
thymic squamous cell carcinoma (2 papers, 2020 to 2023). "For the thymic squamous cell carcinoma subgroup, the sensitivity of EZH2 staining in ≥80% of tumor cells was 92%." (PMID 37190202, 2023).
thyroid tumor (2 papers, 2017 to 2019). A benign or malignant neoplasm affecting the thyroid gland. "Taken together, all these data lead to the conclusion that targeting EZH2 by overexpression of miR‐124/506 or EPZ‐6438 treatment inhibits the proliferation ability of sorafenib resistant thyroid tumour cells via epigenetic regulation." (PMID 31087496, 2019). "Furthermore, we demonstrated that the combined treatment of sorafenib with miR‐124/506 mimics or EZH2 inhibitor could efficiently improve the sensitivity of sorafenib resistant thyroid tumour cells for sorafenib treatment in vitro and in vivo." (PMID 31087496, 2019). "Therefore, to verify this identification of EZH2 in our study, we detected the expression of EZH2 in nthy-ori 3-1 and BCPAP cells using an immunofluorescence assay and western blot, and observed that EZH2 was expressed higher in thyroid tumor cells compared to normal cells." (PMID 28416772, 2017).
transitional cell carcinoma (2 papers, 2012 to 2014). A malignant neoplasm arising from the transitional epithelium, usually affecting the urinary bladder, ureter, or renal pelvis. "All the investigated metastatic adenocarcinomas (from colon, pancreas, breast and lung) were positive for EZH2 as well as the single examined transitional cell carcinoma metastasis." (PMID 22809481, 2012). "EZH2 expression level in urothelial cell carcinoma (UCC) is highly correlated with tumor aggressiveness, but it has not been determined if specific EZH2 genetic variants are associated with UCC risk." (PMID 24691023, 2014).
ulcerative colitis (2 papers, 2016 to 2023). An inflammatory bowel disease involving the mucosal surface of the large intestine and rectum. "In ulcerative colitis, EZH2 reduces colonic inflammation through the Atg5-NLRP3 axis." (PMID 38037161, 2023).
undifferentiated carcinoma (2 papers, 2023 to 2024). A usually aggressive malignant epithelial neoplasm composed of atypical cells which do not display evidence of glandular, squamous, or transitional cell differentiation. "Furthermore, by integrating our study findings with previously known characteristics of undifferentiated carcinoma in the sinonasal tract, we propose that EZH2‐activated SNUC represents a molecular subset of SNUC and its analogues." (PMID 39565059, 2024).
uterine corpus endometrial carcinoma (2 papers, 2018 to 2021). A endometrial carcinoma (disease) that involves the body of uterus. "For the uterine corpus endometrial carcinoma, high expression of EZH2 was correlated with poor survival, although higher expression of EED was associated with a longer survival." (PMID 34202528, 2021).
Waldenstrom macroglobulinaemia (2 papers, 2022 to 2023). "In Waldenstrom macroglobulinemia, EZH2 promotes the expression of pro-apoptotic genes, reduces the sensitivity of tumor cells to external toxicity-inducing signals, and escapes NK cell-mediated death, enabling immune escape, which makes EZH2 a potential target for chemosensitization." (PMID 37239949, 2023). "Our results revealed that Ezh2 inhibition increases PRDM1 and downregulates SPIB, suggesting that further investigation of Ezh2 inhibitors in the context of ABC DLBCL and Waldenstrom macroglobulinaemia could be informative." (PMID 35831623, 2022).
acquired immunodeficiency syndrome (1 paper, 2024). "In acquired immunodeficiency syndrome (AIDS), the phase segregation property of CBX4 allows it to recruit the catalytic subunit EZH2 at the retroviral HIV-1 promoter, which plays a key role in EZH2 SUMOylation and HIV-1 latency." (PMID 38347544, 2024).
acute erythroleukemia (1 paper, 2017). "Further qPCR analysis showed that the expression of MYCN had positive correlation with the expression of EZH2 in the patients with acute erythroleukemia." (PMID 29022893, 2017).
acute GVHD (1 paper, 2021). "However, the recipient EZH2 histone methyltransferase gene SNP, which encodes the D185H substitution, exhibited a low p-value in regression analysis of grade 2–4 acute graft-versus-host disease (p = 0.010)." (PMID 34206082, 2021).
acute megakaryoblastic leukemia (1 paper, 2017). Acute megakaryoblastic leukemia (AMKL) is a form of acute myeloid leukemia (AML) that occurs predominantly in childhood and particularly in children with Down syndrome (DS-AMKL). "EZH2 mutation was more frequently detected in acute megakaryoblastic leukemia (AMKL) and AMKL with Down Syndrome (DS-AMKL), 16 and 33% respectively." (PMID 29270125, 2017).
adenomyosis (1 paper, 2025). The growth of endometrial tissue inside the muscular wall of the uterine corpus. "However, both conditions show dysregulation of EZH2-mediated chromatin silencing—via lncRNAs like TUG1 in adenomyosis and DALI in fibroids —suggesting that epigenetic control of smooth muscle identity may be a shared vulnerability." (PMID 41226749, 2025).
adenosis (1 paper, 2016). "The expression of EZH2 in 20 benign breast lesions comprising of adenosis and usual ductal hyperplasia (UDH) was also assessed." (PMID 27113214, 2016).
adenovirus infection (1 paper, 2024). "Furthermore, EZH2 adenovirus infection further increased EZH2 expression in the aortic tissues of USP7-depleted AS mice." (PMID 39310812, 2024).
adrenocortical adenoma (1 paper, 2025). "Accordingly, gene expression analysis indicated that EZH2 and SLC7A11 are upregulated in ACC in comparison to normal adrenal (NC) and adrenocortical adenoma (ACA)." (PMID 40229247, 2025).
allergic contact dermatitis (1 paper, 2016). An inflammatory skin condition caused by an immune response to direct contact between the skin and an allergen. "Since LCs have been implicated in the regulation of tolerance induction to skin sensitizers, Ezh2-regulated LC migration may be relevant for the disease progression of allergic contact dermatitis." (PMID 26993608, 2016).
aneurysm (1 paper, 2024). Bulging or ballooning in an area of an artery secondary to arterial wall weakening. "SM-22α expression negatively correlates with aneurysm size, and EZH2 inhibition can enhance SM-22α expression." (PMID 38994197, 2024).
aplastic anemia (1 paper, 2016). Anemia resulting from bone marrow failure (aplastic or hypoplastic bone marrow). "Interestingly, enhancement of Th1 differentiation through EZH2 was associated with the development of T cell-mediated aplastic anemia in transgenic mouse models, suggesting that targeting EZH2 might be a possible therapeutic approach for the treatment of aplastic anemia." (PMID 27199994, 2016).
Arrhythmia (1 paper, 2025). Any cardiac rhythm other than the normal sinus rhythm. "Therefore targeting interventions of these pathways, suchas EZH2 inhibitors, Sirt1 activators, and Nedd4-2 modulators, will be the subjectof future studies in an attempt to develop new therapeutic strategies for thetreatment of arrhythmias in clinical practice." (PMID 40630435, 2025).
artery disease (1 paper, 2021). "In contrary artery disease—a condition associated with EndMT1,26—the reciprocity between MAPK7 and EZH2 is disturbed, resulting in elevated expression of DUSP-1 and EZH2 and the decreased expression of MAPK7." (PMID 34493753, 2021).
atherosclerotic heart disease (1 paper, 2016). "In conclusion, our findings obtained from apoE−/− mice provide epigenetic insights into how EZH2 increases the risk of atherosclerotic heart disease." (PMID 27295295, 2016).
atypical ductal hyperplasia (1 paper, 2023). Atypical ductal hyperplasia is an atypical proliferative lesion that falls in between the continuum from normal hyperplasia to low grade ductal carcinoma in situ. "Besides that, the expression of the protein enhancer of zeste homolog 2 (EZH2) is elevated in premalignant atypical ductal hyperplasia (ADH) and even higher in DCIS compared to normal epithelium." (PMID 38169859, 2023).
Azoospermia (1 paper, 2025). Absence of any measurable level of sperm,whereby spermatozoa cannot be observed even after centrifugation of the semen pellet. "Immunofluorescence staining of the testes revealed that the histone methyltransferase EZH2 and Leydig cell marker gene IL6 or HDAC2 were upregulated in azoospermia." (PMID 40756901, 2025).
benign prostatic hyperplasia (1 paper, 2026). A non-cancerous nodular enlargement of the prostate gland. "To investigate the potential role of EZH2 in m6A regulation, we first measured the m6A levels in a panel of PCa cell lines along with human normal primary prostate epithelial cells (PrEC) and benign prostatic hyperplasia cell line BPH-1 using m6A ELISA." (PMID 41252201, 2026).
brain glioma (1 paper, 2021). A malignant glioma that involves the brain. "The suppression of EZH2 gene secretion was capable of reversing TMZ resistance in patients with brain glioma." (PMID 34745848, 2021). "It was established that in vitro administration of the EZH2 inhibitor DZNep was capable of suppressing the proliferation potency of GSCs in an analysis of brain glioma." (PMID 34745848, 2021). "Furthermore, the suppression of EZH2 gene secretion was capable of reversing temozolomide (TMZ) resistance in patients with brain glioma." (PMID 34745848, 2021).
brain ischemia (1 paper, 2019). Diminished or absent blood supply to the brain caused by obstruction (thrombosis or embolism) of an artery resulting in neurologic damage. "Interestingly, EZH2 and Polycomb also play a protective role in brain ischemia." (PMID 31891591, 2019).
brainstem gliomas (1 paper, 2022).
central nervous system lymphoma (1 paper, 2016). "The mutation of EZH2 were related to primary central nervous system lymphoma." (PMID 27266699, 2016).
cervix adenocarcinoma (1 paper, 2015). "Western blotting was performed to detect BBAP levels using extracts prepared from EZH2GOF lines (Karpas-422, SUDHL4), a chemosensitive EZH2 wild-type DLBCL line (SUDHL8), NALM6 (a pre-B ALL line), HeLa (a cervix adenocarcinoma line), mouse NIH3T3 cells and mouse fibrosarcoma cells." (PMID 25605023, 2015).
childhood leukemia (1 paper, 2025). An acute or chronic leukemia that occurs during childhood. "These unexpected results led us to investigate whether the blockade of EZH2 may lead to the activation of alternative oncogenic pathways, such as FLT3 and its downstream signaling, previously reported for childhood leukemia." (PMID 40722046, 2025).
Cirrhosis (1 paper, 2024). A chronic disorder of the liver in which liver tissue becomes scarred and is partially replaced by regenerative nodules and fibrotic tissue resulting in loss of liver function. "Intriguingly, a subsequent analysis using the GSE63898 cohort reaffirmed that PRC2 subunits inclusive of EZH2 displayed a higher expression in HCC than in cirrhosis, often considered an HCC precursor state." (PMID 39516467, 2024).
CNS DLBCL (1 paper, 2021). "The CNS DLBCL-specific miR-26a downregulation that we present here is also in line with the previous studies suggesting an MYC-miR-26a-EZH2 positive feedback loop in aggressive B-NHLs." (PMID 34572608, 2021).
co-infection (1 paper, 2019). "Upon intratumor injection with cisplatin, the size of xenograft tumors in co-infection group with p-EZH2 and si-SLC34A2 abolished the reduction in xenograft tumors resulting from si-SLC34A2 infection alone." (PMID 30038060, 2019). "Cell viability of si-SLC34A2 cells was significantly reduced, while the co-infection with p-EZH2 and si-SLC34A2 reversed the cell viability." (PMID 30038060, 2019). "Similarly, co-infection group with p-EZH2 and si-SLC34A2 relieved the higher TUNEL index due to si-SLC34A2 infection alone." (PMID 30038060, 2019).
congestive heart failure (1 paper, 2025). Failure of the heart to pump a sufficient amount of blood to meet the needs of the body tissues, resulting in tissue congestion and edema. "The congestive heart failure-associated targets were Dnmt1, Hdac1, Hdac4, Ezh2, Sirt3, Kdm2a, Prkca and Prkcb (9.8% of total targets)." (PMID 40076868, 2025).
corticotropic adenoma (1 paper, 2015). "Our results suggest a potential role of EZH2 as a target for new drug-based treatment strategies in highly proliferating PA, especially corticotropic adenoma subtypes." (PMID 26593398, 2015). "Furthermore, we were able to show that inhibition of EZH2 leads to decreased growth and cell viability of AtT-20 cells, suggesting a potentially new target for drug treatment in corticotropic adenomas." (PMID 26593398, 2015).
Cri-du-chat syndrome (1 paper, 2022). Monosomy 5p, also known as Cri du chat syndrome, is a rare autosomal deletion syndrome characterized by a mewing cry (cri du chat) in infancy, multiple congenital anomalies, intellectual disability, microcephaly, and facial dysmorphism. "BRD9 has in fact been shown to regulate EZH2 expression by binding together with CTCF in an EZH2 enhancer, but we do not know if EZH2 expression changes contribute to Cri du chat syndrome pathogenesis." (PMID 36242045, 2022).
cryptorchidism (1 paper, 2022). The failure of one or both testes of a male fetus to descend from the abdomen into the scrotum during the late part of pregnancy. "Here, we found that EZH2 mRNA and protein expression were both significantly decreased in the testicular tissues of patients with cryptorchidism." (PMID 35415251, 2022). "The results of RT-PCR, western blot, and immunohistochemistry showed that miR-22-5p was increased while EZH2 decreased in the testicular tissues of patients with cryptorchidism." (PMID 35415251, 2022).
delirium (1 paper, 2018). A disorder characterized by confusion; inattentiveness; disorientation; illusions; hallucinations; agitation; and in some instances autonomic nervous system overactivity. "TR4 and EZH2 could therefore be interesting candidates to predict risk of developing postoperative delirium." (PMID 30367354, 2018). "However, the results already suggest that TR4 and EZH2 levels could be used to preoperatively identify patients that are at risk of developing postoperative delirium." (PMID 30367354, 2018). "Both TR4 and EZH2 were elevated in serum in the patients with postoperative delirium; however, the patients that developed postoperative delirium had elevated levels of both TR4 and EZH2 already preoperatively." (PMID 30367354, 2018). "Interestingly, TR4 and EZH2 differed already preoperatively in the patients that developed delirium after operation." (PMID 30367354, 2018). "TR4 and EZH2 were still significantly higher in patients with postoperative delirium compared to those without after FDR correction." (PMID 30367354, 2018). "For delirium, the levels of three proteins differed in serum of affected compared to non-affected patients at uncorrected p < 0.01 (TR4, EZH2, and SOX10) and 15 at p < 0.05." (PMID 30367354, 2018). "There were markers in both serum and CSF that differed between the affected and non-affected patients (SCI; IL6, GFAP, CSPG4, delirium; TR4, EZH2, hallucinations; NF1)." (PMID 30367354, 2018).
demyelinating disease (1 paper, 2025). A broad group of disorders that affect the myelin sheaths that cover the neurons. "In demyelinating diseases, inflammatory microenvironments lead to decreased EZH2 expression, contributing to remyelination failure." (PMID 41471322, 2025). "For instance, the synergy between EZH2 and HDAC requires dual-effect inhibitors, yet existing DNMT1/HDAC inhibitors have only been validated in tumor models, lacking data for demyelinating diseases." (PMID 41471322, 2025).